CREBL2 (cAMP responsive element binding protein like 2)
Description:
Probable regulator of CREB1 transcriptional activity which is involved in adipose cells differentiation. May also play a regulatory role in the cell cycle. Identification in a chromosomal region frequently deleted in various cancers suggests that it might act as a tumor suppressor.
Tractability: No criterion of Open Targets' tractability assessment is met for any kind of drug.
Gene: Protein-coding gene on chromosome 12 (12,611,827 to 12,645,108, forward strand). Ensembl gene ENSG00000111269.
Subcellular location: Nucleus
Subcellular location (Human Protein Atlas): Mitochondria; Cytosol; Nucleoplasm
Gene Ontology:
Molecular function: protein binding; DNA-binding transcription factor activity; DNA-binding transcription factor activity, RNA polymerase II-specific
Biological process: DNA-templated transcription; positive regulation of D-glucose import; positive regulation of DNA-templated transcription; positive regulation of fat cell differentiation; positive regulation of lipid biosynthetic process; positive regulation of peptidyl-serine phosphorylation; protein stabilization; regulation of DNA-templated transcription; signal transduction; regulation of transcription by RNA polymerase II
Cellular component: chromatin; nucleus
Genetic constraint (gnomAD): Loss-of-function variants: 2 observed, 14.76 expected, observed/expected ratio (o/e) 0.14, 90% interval 0.054 to 0.43. The upper end of that interval is the gene's LOEUF score, 0.43, which puts it in group 1 of 6, group 1 being the genes least tolerant of losing a copy. Missense variants: 84 observed, 144.09 expected, observed/expected ratio (o/e) 0.58, 90% interval 0.49 to 0.7. Synonymous variants: 41 observed, 47.47 expected, observed/expected ratio (o/e) 0.86, 90% interval 0.67 to 1.12.
Homologues: Orthologues: dog CREBL2 (99% identical), macaque CREBL2 (99% identical), pig CREBL2 (97% identical), rabbit CREBL2 (97% identical), chimpanzee CREBL2 (96% identical), guinea pig CREBL2 (95% identical), mouse Crebl2 (93% identical), rat Crebl2 (93% identical), zebrafish crebl2 (81% identical), tropical clawed frog crebl2 (78% identical), Drosophila melanogaster REPTOR-BP (4% identical).
Diseases named in the same sentence as CREBL2 in open-access papers:
CREBL2 is named in the same sentence as 8 diseases in open-access papers, as found by Europe PMC text mining. Sharing a sentence is not in itself a finding about the gene and the disease. The quoted sentences say what the papers report.
bile duct cancer (1 paper, 2024). "Moreover, DNA methylation at cg23320499 was negatively correlated with the expression of CREBL2 in several cancer types such as thymoma (p-value = 8.71e-11, r-value = -0.6) and bile duct cancer (p-value = 1.54e-02, r-value = -0.5)." (PMID 39556603, 2024).
Cirrhosis (1 paper, 2023). A chronic disorder of the liver in which liver tissue becomes scarred and is partially replaced by regenerative nodules and fibrotic tissue resulting in loss of liver function. "The miR-17-92 cluster, which is upregulated in cirrhosis, is a well-characterized oncomiR due to its capacity to inhibit the expression of cAMP Responsive Element Binding Protein Like 2 (CREBL2), Proline Rich and Gla Domain 1 (PRRG1), and Netrin 4 (NTN4)." (PMID 38067261, 2023).
hepatoma (1 paper, 2019). "In Hepa1-6 hepatoma cells, Crebl2 knockdown also leads to elevated triglyceride levels." (PMID 31882710, 2019).
meningioma (1 paper, 2023). A generally slow growing tumor attached to the dura mater. "Interestingly, seven of the meningioma-associated antigens were shared between all WHO grades (NMA2, TBX15/18, XXLT1, SLC25A44, RHOD, CREBL2, and PLCD4)." (PMID 37368072, 2023).
peripheral nerve injury (1 paper, 2023). Injury to a peripheral nerve. "In addition, Crebl2 was identified as a miR-195-5p’s downstream functional target gene, providing insights into cellular metabolism and expanding understanding of the molecular changes associated with peripheral nerve injury." (PMID 37469605, 2023).
cancer (5 papers, 2016 to 2024). A tumor composed of atypical neoplastic, often pleomorphic cells that invade other tissues. "Others that have been indirectly linked to cancer include HIST1H2AD, two zinc finger proteins (ZCCHC3, ZNF552), and CSRP2, CREBL2, and SERTAD3." (PMID 29282095, 2017). "The genomic alterations of PDGFRA, PARP1, CREBL2, and DAB1 cooperatively contributed to the abnormality of cancer hallmarks." (PMID 37491836, 2023). "Based on the genomic expression data in the whole cancer population, the top prognostic genes were identified, such as FOXM1, CBX7, CREBL2 and SKP2, which were consistent with previous studies." (PMID 27322207, 2016).
CREBL2 also shares sentences with these, for which no sentence is quoted: endometrioid ovarian cancer (1 paper); thymoma (1).